ENSG00000274430
Gene: Miscellaneous RNA gene on chromosome X (73,944,332 to 73,944,466, forward strand). Ensembl gene ENSG00000274430.
Gene Ontology:
Biological process: positive regulation of gene expression